GDF15 (growth differentiation factor 15)
Diseases named in the same sentence as GDF15 in open-access papers (continued):
Sharing a sentence is not in itself a finding about the gene and the disease.
Sepsis (continued). "The anti-inflammatory effect of glycolysis inhibitor 2-DG on AMs during sepsis was mediated by GDF15 via inducing the phosphorylation of the α-subunit of eukaryotic initiation factor 2 (eIF2α) and the expression of activating transcription factor 4 (ATF4)." (PMID 38725041, 2024). "We discovered that GDF15 limited the glycolytic flux in AMs and mediated the beneficial effects of 2-DG on inflammatory response of AMs in sepsis-induced lung injury." (PMID 38725041, 2024). "GDF-15 KO mice were protected against cecal ligation- and puncture-induced sepsis, showing less severe symptoms, lower markers of inflammation, and lower bacterial load." (PMID 39000420, 2024). "In the present study, we found that although the plasma levels of GDF15 were positively correlated with the severity of patients with sepsis, recombinant GDF15 administration in vivo alleviated sepsis-induced systemic inflammation and lung injury." (PMID 38725041, 2024). "A lower expression of another pivotal gene involved in metabolism and immune response control, growth differentiation factor 15 (gdf15), which is also a marker of sepsis severity, was observed in the resistant family." (PMID 39712009, 2024). "Conversely, animal studies on GDF-15 modulation in sepsis and cancer display significant discrepancies." (PMID 39000420, 2024). "The increase of serum GDF15 level is closely related to the severity and mortality of sepsis patients, and GDF15 can be used as a prognostic indicator of sepsis." (PMID 37691951, 2023). "Remarkably, the GDF15 is regarded as an inducer of sepsis tolerance through the modulation of metabolic alterations in severe septic infections." (PMID 36140453, 2022). "GDF-15 also reduces LPS-induced sepsis responses in mice and suppresses NLRP3 inflammasome activation and inflammatory responses in adipose tissue." (PMID 35821815, 2022). "Studies on GDF-15 levels during sepsis illustrate the hormetic role of GDF-15 during infection, with low levels being protective while high levels being associated with disease severity." (PMID 35251002, 2022). "The peak circulating concentrations of human GDF15 achieved in the mice were comparable to those reported in states such as severe sepsis." (PMID 34187898, 2021). "We drew the ROC curve to further analyze the dynamic GDF15 levels to distinguish between sepsis and septic shock." (PMID 34566964, 2021). "Our study shows that GDF15 is increased in patients with sepsis, and it is correlated with PCT, SOFA scores, and many laboratory indexes." (PMID 34566964, 2021). "This article aims to explore the clinical value of GDF15 in sepsis and to preliminarily explore its prospective regulatory effect on macrophage inflammation and its functions." (PMID 34566964, 2021). "In summary, this study found that the increase of GDF15 in serum of patients was closely related to organ injury and severity of sepsis." (PMID 34566964, 2021). "At the same time, we observed that the concentration of GDF15 in sepsis patients with different PCT levels is also different." (PMID 34566964, 2021). "The authors demonstrated the induction of GDF15 during sepsis and its tissue-protective role, defining GDF15 as an “inflammation-induced central mediator of tissue tolerance”." (PMID 34445593, 2021). "The results show that the dynamic monitoring of GDF15 has little difference between the general sepsis group and the septic shock group, but the trend is consistent with the severity of the disease." (PMID 34566964, 2021). "We have observed that serum GDF15 levels in patients with sepsis are elevated, which is consistent with the results of previous studies." (PMID 34566964, 2021). "Inflammation induced GDF15, and GDF15 are necessary for surviving both bacterial and viral infections, as well as sepsis." (PMID 34445593, 2021).
Sepsis (continued). "We consider that GDF15 plays a protective role in sepsis; it can inhibit the M1 polarization of macrophages as well as the phosphorylation of JAK1/STAT3 signaling pathway and nuclear translocation of NF-κB p65 to alleviate inflammation." (PMID 34566964, 2021). "We demonstrated that the GDF-15 concentration is also an effective predictor for mortality in critically ill patients with AKI; causes of AKI were various, including sepsis and ischemia." (PMID 34441955, 2021). "The levels of GDF15 in the shock group increased even after admission, while the general sepsis group showed a downward trend, which was more obvious in the survival group and the death group." (PMID 34566964, 2021). "Taken together, it seems more inclined to consider that GDF15 is involved in the progression of sepsis as a protective factor at present." (PMID 34566964, 2021). "We draw the ROC curve to analyze the diagnostic value of GDF15 for sepsis, and then combined it with inflammation indicators and SOFA scores to analyze the enhancement effect of GDF15 on the diagnostic value of sepsis." (PMID 34566964, 2021). "GDF15 also has a high AUC in the diagnosis of sepsis, which can be further improved by combining with other indicators." (PMID 34566964, 2021). "The anti-inflammatory role of GDF15 was highlighted in an experimental sepsis model in GDF15 knockout mice." (PMID 34445593, 2021). "The dynamic monitoring of GDF15 levels can play an important role in the judgment and prognosis of sepsis." (PMID 34566964, 2021). "The results showed that the serum GDF15 levels were significantly increased in the sepsis group, which was correlated with laboratory indexes of organ damage, coagulation indexes, inflammatory factors, and SOFA score." (PMID 34566964, 2021). "The prognostic value of GDF15 level of Day 7 in sepsis was better than that of the other two points of time." (PMID 34566964, 2021). "On the whole, the level of GDF15 in septic shock group showed an upward trend, while the level of GDF15 in sepsis group changed little." (PMID 34566964, 2021). "We divided the patients under dynamic monitoring into sepsis group and septic shock group, and analyzed the GDF15 levels of the two groups of patients on the 1st, 3rd, and 7th days after admission and treatment." (PMID 34566964, 2021). "To explore the role of GDF15 in sepsis, we first measured its levels at 4, 8, and 24 h in the peripheral blood of mice subjected to cecal ligation and puncture (CLP) and in mice subjected to sham operation alone." (PMID 32424099, 2020). "We found that similarly to TNF in serum after CLP, GDF15 levels were significantly increased, in agreement with the findings in sepsis patients." (PMID 32424099, 2020). "Growth and Differentiation Factor 15 (GDF15) is known to regulate metabolism and energy homeostasis and thus is a good candidate to play a role in sepsis." (PMID 32424099, 2020). "We found significant differences in GDF15 levels between AA and HC patients (P < 0.0001) and between AA and sepsis patients (P < 0.0001)." (PMID 32424099, 2020). "For example, human patients that died during the course of sepsis treatment had significantly higher serum GDF15 levels on admittance to the ICU than survivors." (PMID 31947892, 2020). "While these findings are intriguing, the opposite effect was observed in a polymicrobial model of sepsis undertaken in Gdf15-/-mice." (PMID 32310257, 2020). "Induction of GDF-15 during sepsis and its tissue-protective role were very recently confirmed, where the authors described GDF-15 as an “inflammation-induced central mediator of tissue tolerance”." (PMID 32508832, 2020). "Given the role of GDF15 in metabolism regulation and in cachexia during late stages of cancer, features that also occur in sepsis, elucidation of the possible mechanistic role of GDF15 in sepsis is of great importance." (PMID 32424099, 2020).
Sepsis (continued). "GDF-15 also serves as biomarker in other critical disease conditions, such as acute pulmonary embolism, acute respiratory distress syndrome, or sepsis." (PMID 31624933, 2019). "GDF-15 serum concentrations are significantly increased in critically ill patients, especially in sepsis." (PMID 29180833, 2017). "Serum concentrations of GDF-15 can predict poor survival in chronic diseases, but its role in sepsis is obscure." (PMID 29180833, 2017). "The Kaplan-Meier survival curve analysis confirmed that high GDF-15 levels (>3624 pg/mL) were strongly associated with ICU mortality in all patients and sepsis patients." (PMID 29180833, 2017). "In the subgroup of sepsis patients, GDF-15 remained independent when assessed together with the same set of covariates with an HR of 3.16 (95% CI 1.10–9.07)." (PMID 29180833, 2017). "To determine the predictive value of GDF-15 in identifying sepsis at admission, we conducted a ROC analysis comparing GDF-15 with classical markers such as procalcitonin and C-reactive protein (CRP)." (PMID 29180833, 2017). "In fact, two smaller studies on 15 and 14 sepsis patients had already indicated increased levels of GDF-15 at the ICU." (PMID 29180833, 2017). "However, experimental studies using genetic ablation or antibody-mediated neutralization of GDF15 in sepsis models have demonstrated negligible effects on appetite or body weight, complicating the translational relevance of this approach." (PMID 41301477, 2025). "Thus, the potential of GDF15 as a complementary biomarker in sepsis pathophysiology is investigated." (PMID 40941711, 2025). "Supplementation of GDF15 diminished inflammation and lung injury in LPS-induced mouse sepsis model." (PMID 38725041, 2024). "Several other studies have proposed GDF-15 as a protective factor in sepsis." (PMID 39000420, 2024). "In the current study, we provided a better understanding of GDF15 in sepsis-induced lung injury." (PMID 38725041, 2024). "There is abundant evidence that GDF15 signaling can ameliorate different acute tissue injuries by dampening excessive inflammation such as myocardial ischemia–reperfusion injury, sepsis-induced acute lung injury, and toxin-induced liver injury." (PMID 39643709, 2024). "However, recent evidence has deepened the knowledge of the mechanism of GDF-15 in sepsis, and this has highlighted an exciting opportunity to redirect the therapy of such a complex disease." (PMID 39000420, 2024). "Previous studies had identified several biomarkers such as oncostatin M (OSM), apoptosis inhibitor of the macrophage (AIM/CD5L), interleukin-26 (IL-26), interleukin-17D (IL-17D), interleukin-37 (IL-37), and growth differentiation factor-15 (GDF-15) as potential predictors of sepsis prognosis." (PMID 38318247, 2024). "Interestingly, a change to fat utilisation has also been reported in response to repeat dosing with exogenous GDF15, including in pair-fed animals, and has been suggested as an important response to GDF15 in models of both septicaemia and cancer." (PMID 39737892, 2024). "Since the plasma levels of GDF15 in patients with sepsis are correlated with the levels of lactate, the product of glycolysis, we speculated the regulatory interaction between GDF15 and glycolytic metabolism." (PMID 38725041, 2024). "This study demonstrated that GDF15 inhibited glycolysis and NF-κB/MAPKs signaling via activating AMP-activated protein kinase (AMPK), thereby alleviating the inflammatory responses of AMs and sepsis-associated lung injury." (PMID 38725041, 2024). "Our findings imply that GDF15 might serve as a potential target for sepsis-related lung injury therapies." (PMID 38725041, 2024). "Furthermore, GDF15 alleviated inflammatory response of AMs in sepsis-induced lung injury via AMPK activation-mediated inhibition of glycolysis and MAPKs/NF-κB signaling." (PMID 38725041, 2024).
Sepsis (continued). "It is possible that GDF-15 released from repeated mild mitochondrial perturbation in sepsis may offer a protective role based on mitohormesis theory and excessive release to detrimental outcomes." (PMID 37152099, 2023). "The pathological mechanism of sepsis in humans may be mediated through the mitochondrial stress response where it induces the release of distinct secretory proteins from cells including GDF-15." (PMID 37152099, 2023). "In a similar way, GDF15 serum level had been reported to be augmented in septic patients, which might be a compensatory mechanism against immune dysregulation in sepsis." (PMID 36140453, 2022). "In contrast, GDF15 has also been proposed as a central mediator of tissue tolerance induced by inflammation, by protecting against bacterial and viral infections, as well as sepsis, in mouse models." (PMID 35937703, 2022). "GDF-15 levels are significantly increased in patients with various infections and sepsis." (PMID 35251002, 2022). "Dynamic monitoring of GDF15 can indicate the trend of the disease and has a good diagnosis and prognostic value, even may be a biomarker of sepsis in the future." (PMID 34566964, 2021). "This study found that GDF15 is positively correlated with IL-6 and IL-10, which may be due to the rapid increase of cytokines after the cytokine storm in sepsis." (PMID 34566964, 2021). "In summary, our study found that GDF15 has good clinical application value in sepsis and plays a protective role in the development of sepsis by regulating the functions of macrophages and inhibiting the activation of JAK1/STAT3 pathway and nuclear translocation of NF-κB p65." (PMID 34566964, 2021). "Several studies have analyzed the diagnostic and prognostic value of GDF15 in sepsis, but no dynamic monitoring analysis has been carried out." (PMID 34566964, 2021). "GDF-15 is recently identified as a prognostic biomarker for cardiovascular diseases, end-stage kidney disease, acute respiratory distress syndrome, and sepsis." (PMID 34441955, 2021). "In the present study, we suspect that GDF15 may regulate the occurrence and development of sepsis through macrophages." (PMID 34566964, 2021). "Several literatures concluded that the increase of GDF15 could protect organ damage in sepsis, and some researchers proposed that GDF15 played a protective role in sepsis by improving the tolerance to inflammation." (PMID 34566964, 2021). "ROC curve analysis of dynamic monitoring GDF15 in sepsis and septic shock." (PMID 34566964, 2021). "What is more, rGDF15 could improve phagocytosis and bactericidal function of macrophages, which supports the conclusion that GDF15 plays a protective role in sepsis together with the results above." (PMID 34566964, 2021). "Furthermore, the rates of severe sepsis and vasopressor use were significantly higher in the patients with preoperatively raised GDF-15 levels." (PMID 34221186, 2021). "ROC curve analysis of dynamic monitoring GDF15 in the prognosis of sepsis." (PMID 34566964, 2021). "Our study found that GDF15 had high clinical value in sepsis, and its dynamic monitoring could indicate the direction of the disease." (PMID 34566964, 2021). "Our results identify GDF15 as a potential target to improve sepsis treatment." (PMID 32424099, 2020). "The common pathological features between cancer (where GDF15 has a demonstrated role) and sepsis led us to ask whether GDF15 level is regulated in sepsis and whether it plays a causative role in its pathophysiology." (PMID 32424099, 2020). "At a log2FC>2 (adjusted P < 0.05) MAPK related genes F2rl1, Adm (marked as multi, as it was picked up for term searches “metabolic,” “hypoxia,” and “MAPK”), Mapk4, Gdf15, Dusp10, and Dusp8 were up-regulated in Isoflurane-Sepsis compared to only 2 genes in the Propofol-Sepsis group." (PMID 33392215, 2020). "It has also been demonstrated that GDF15 may have prognostic utility in patients with sepsis, with elevated levels predicting mortality." (PMID 32310257, 2020).
Sepsis (continued). "Our study also not did not address the mechanistic role of GDF15 in sepsis caused by other groups of pathogens, including viruses and fungi, which are increasingly frequent causes of this condition." (PMID 32424099, 2020). "Moderate-sized cohort studies have demonstrated that GDF15 is elevated in critically ill patients with the acute respiratory distress syndrome, a large number of whom have an infectious illness, and in critically ill patients with sepsis." (PMID 32310257, 2020). "A recent small study found increased GDF-15 levels in 15 patients with sepsis." (PMID 29180833, 2017). "As all types of organ failure (heart, lung, liver, and kidney) related to high GDF-15 are relevant for the prognosis of sepsis, we hypothesized that GDF-15 might represent an interesting prognostic biomarker in critically ill patients with sepsis." (PMID 29180833, 2017). "Although stone-specific ROC data for GDF-15 are lacking in the literature, analogous studies in CKD and sepsis have reported high diagnostic accuracy for GDF-15, supporting the plausibility of our findings and reinforcing its potential clinical value in acute obstructive urologic settings." (PMID 41515626, 2026). "Notably, the significant decrease in GDF15 levels starting from Day 3 and becoming more pronounced after Day 7 suggests a potential compensatory or anti-inflammatory role of this molecule during the resolution phase of sepsis." (PMID 40941711, 2025). "Our findings indicate that GDF15 may serve as a valuable biomarker for both monitoring the resolution phase of inflammation and assessing renal dysfunction in the clinical management of sepsis." (PMID 40941711, 2025). "In sepsis, a rise in GDF-15 may play a role in metabolic adaptation and organ protection." (PMID 37152099, 2023). "Therefore, GDF15 has a role in inflammation-driven states and is a biomarker for sepsis." (PMID 34445593, 2021). "At the same time, GDF15 could alleviate the inflammatory response by regulating the function of macrophages and reducing the phosphorylation of JAK1/STAT3 and the nuclear translocation of NF-κB p65, which confirmed that GDF15 played a protective role in sepsis from the cellular level." (PMID 34566964, 2021). "Moreover, one of the most highly overexpressed genes after LPS challenge was GDF15, which was previously identified as a metabolic regulator involved in tolerance to LPS-induced sepsis in vertebrates through the alteration of lipid and glucose metabolism to avoid inflammatory damage." (PMID 33391272, 2020). "We then turned to the mechanistic role of GDF15 in sepsis, as the strongly increased secretion could mean either that this factor is involved in a compensatory response to a stress (infection) challenge or that it plays an active part in increasing the severity of infection." (PMID 32424099, 2020). "We therefore hypothesized that GDF-15 could be a useful novel biomarker in critically ill patients that might integrate information on multiorgan dysfunction that is prognostically relevant especially in sepsis and septic shock." (PMID 29180833, 2017). "Growth differentiation factor 15 (GDF15), recognized as a stress response cytokine, mitigates sepsis-induced lung injury through the promotion of AMPK phosphorylation, inhibition of glycolysis in alveolar macrophages, and attenuation of NF-κB/MAPKs signaling." (PMID 39712019, 2024). "In turn, GDF15 inhibited glycolysis and NF-κB/MAPKs signaling through AMPK activation, thereby alleviating the inflammatory response and lung injury in sepsis." (PMID 38725041, 2024). "Growth differentiation factor 15 (GDF15) is involved in the occurrence and development of many diseases, and there are few studies on its relationship with sepsis." (PMID 34566964, 2021).